ALB (albumin)
Diseases named in the same sentence as ALB in open-access papers (continued):
Sharing a sentence is not in itself a finding about the gene and the disease.
diabetes (continued). "There was a significant difference in HbA1c level, but not FPG level, among the albumin intervals, and the mean HbA1c levels significantly decreased from 5.86 to 5.67% (P < 0.001 for the trend), which ranged across the threshold of HbA1c-defined pre-diabetes (5.7%)." (PMID 34055818, 2021). "In conclusion, the quantification of oxidised and non-oxidised Met147 in serum albumin using our LC-MS methodology could be used to assess the degree of intravascular oxidative stress induced by hypoglycaemia and glycaemic fluctuations in diabetes." (PMID 31937809, 2020). "However, while not assessed here, adequate diabetes management goes beyond the management of HbA1c alone and also involves the assessment of renal function (serum creatinine and urine albumin/creatinine ratio), smoking status, foot surveillance, and retinal screening." (PMID 31366676, 2019). "Finally, glycated albumin which is a strong predictor of diabetes was not measured concurrently." (PMID 28430803, 2017). "One such example is poorly controlled diabetes, whereby the nonenzymatic covalent attachment of glucose molecules to albumin, as well as the subsequent oxidation, gives rise to advanced glycation end-products that bind to the albumin surface (also termed “glycated albumin”)." (PMID 28356609, 2017). "Our ELISA results, however, do not support the hypothesis that AGEs on RPCs are the primary neoautoantigens that antibodies in DR patient recognize, because we did not detect appreciable levels of antibodies that bind to albumin modified by glycating metabolites that are characteristic of diabetes." (PMID 26839120, 2016). "In 200 incident hemodialysis patients we used partial least squares discriminant analysis to identify which among 166 metabolites could best discriminate individuals with or without diabetes, and across tertiles of body mass index, serum albumin, total cholesterol, and systolic blood pressure." (PMID 26149577, 2015). "National Institute for Health and Clinical Excellence in England recommends ACE inhibitors/ARBs in patients with diabetes mellitus irrespective of whether they have hypertension or not, if albumin:creatinine ratio is > 2.5 mg/mmol (men) or > 3.5 mg/mmol (women)." (PMID 24955116, 2014). "The scoring system includes: Acute kidney injury (AKI), CRP > 50 mg/L, serum albumin < 2.5 g/dL, ascitic fluid protein < 1.0 g/dL, MELD ≥ 15, diabetes mellitus, multidrug-resistant organisms (MDRO), and non-use of β-blockers (each = 1 point)." (PMID 41353185, 2025). "Depending on the history of CVD the most important predictors for people with diabetes but without a history of CVD included: cystatin C, self-reported health satisfaction, biochemical measures of ill health (e.g. plasma albumin)." (PMID 40082712, 2025). "In conclusion, dapagliflozin reduced proteinuria—both albumin and, as a novelty, non-albumin proteins—in KTR patients with diabetes and without diabetes, with a low rate of side effects." (PMID 40564021, 2025). "In participants without diabetes, lower serum calcium levels were significantly correlated with lower insulin, HbA1c, TC, HDL‐C, LDL‐C, TG, uric acid, urine albumin‐to‐creatinine ratios, and higher eGFRs (all p < 0.05)." (PMID 41000256, 2025). "Among participants with diabetes there was a positive correlation between tubular TMEM16A expression (but not CLCA1) and urinary albumin-to-creatinine ratio (r value 0.39, P = 0.0059)." (PMID 39782685, 2025). "Patient age, body weight, blood pressure, ALB, BUN, triglycerides, total cholesterol, and LDL concentrations, fasting blood glucose, Oxford histologic score and the proportion of patients with diabetes were not significantly different between the groups." (PMID 39048780, 2024). "Patients in the DR group had a higher BUN, serum albumin, creatinine, glycated hemoglobin, ALP, systolic blood pressure, and length of time with diabetes than those in the non-DR group (p < 0.05)." (PMID 38800479, 2024).
diabetes (continued). "Patients without cirrhosis were less likely to have a history of diabetes, and they had lower INR, and higher albumin and platelet counts than patients with cirrhosis." (PMID 37078924, 2023). "Additional one-by-one adjustments for serum albumin, CVD, diabetes, or dialysis treatment did not change the observed associations." (PMID 37181128, 2023). "Another 34 primary MN patients without diabetes were set as control group by PSM(propensity score matching)method(age, gender, serum albumin, urinary protein, eGFR, IFTA score for kidney pathology evaluation were set as control variables)." (PMID 36879071, 2023). "Urine albumin-to-creatinine ratio (ACR), also known as urine microalbumin, is a sign of diabetic nephropathy (DN), which is a prevalent complication of diabetes and can result in end-stage renal disease (ESRD) if not managed." (PMID 37692611, 2023). "But quite a few indicators, such as albumin, PAB and CRP were not statistically different, suggesting that good glycemic control can reduce the adverse effects of diabetes to some extent." (PMID 35308284, 2022). "In patients with diabetes without CKD, mean glucose from CGM is highly correlated with fructosamine (rho 0.85) and glycated albumin (rho 0.87), supporting their role as alternative glycemic markers." (PMID 35414081, 2022). "First, increased urinary albumin excretion has been suggested to be marker of vascular dysfunction and may in fact reflect a widespread vascular process involving the cerebral vasculature, independently of diabetes or hypertension, as shown in studies of people without hypertension or diabetes." (PMID 35346165, 2022). "In conclusion, the emerged simple markers of insulin resistance, TyG index and TG/HDL-C are important predictors of in-hospital death in AMI patients without diabetes after adjusting significant variables such as age, SBP, BUN, WBC, ALT and ALB." (PMID 36438585, 2022). "No statistical differences were observed in hypertension, diabetes mellitus, LVEF, albumin, hyperlipidemia, transient ischemic attack (TIA), cystatin C (Cys-C), D-Dimer, and history of drinking and smoking between two groups (P > 0.05, respectively)." (PMID 36386353, 2022). "The 14 variables (sex, age, albumin, emergency, type of surgery, WBC, Glu, Hb, BMI, total bilirubin, non-independent functional status, diabetes, type of surgery, duration of anesthesia) were matched in constructing PSM cohort." (PMID 36064357, 2022). "Sex, BMI, smoking history, alcohol intake, hypertension, diabetes mellitus, ASA status, CCI, serum albumin, ALT, AST, blood urea, and SCREA were not significantly different between the delirium and non‐delirium groups." (PMID 34415671, 2022). "There were significant differences (P < 0.05) between the participants who had anemia and those who did not have anemia in terms of age, diabetes mellitus, CKD, BMI, eGFR, albumin, glucose, total cholesterol." (PMID 33644094, 2021). "History of prior hip IACSI, age, sex, laterality, alcohol abuse, tobacco use, chronic steroid use, diabetes mellitus, hip trauma, HIV/AIDS, obstructive pulmonary disease, and serum albumin level were not significant." (PMID 34727125, 2021). "In addition, non-survivors with diabetes had multiple abnormal laboratory values related to cardiac, hepatic, and renal impairment, including higher levels of TnT, CK-MB, myoglobulin, NT-proBNP, aspartate aminotransferase, and urea nitrogen and lower levels of albumin." (PMID 34283900, 2021). "In the cohort, patients who developed AKI were elder and exhibited more comorbidities (diabetes mellitus, anemia, and CHF) and lower levels of lymphocyte, serum albumin, eGFR, and haematocrit compared with those who did not develop AKI." (PMID 34316292, 2021). "Other parameters like diabetes, hypertension, duration of HD, body mass index, hemoglobin, eGFR, ejection fraction, high sensitivity CRP and albumin did not significantly affect SPAP, which were determinants for PH." (PMID 33816034, 2021).
diabetes (continued). "Albumin was isolated from type 1 (DM1) and type 2 (DM2) diabetes mellitus (HbA1c > 9%) and non-DM subjects (C)." (PMID 33019603, 2020). "Our results showed that after induction of diabetes, FBS, and HbA1C increased, and serum insulin decreased significantly, but glycosylated albumin and serum BDNF did not change significantly." (PMID 32405353, 2020). "The ages of the four patients with the capsule stuck in the stomach were 61, 66, 72, and 82, and none of these patients had diabetes, CKD, low albumin, or information in the chart suggesting the presence for risk factors for gastric outlet obstruction." (PMID 32064217, 2020). "NFS is calculated as 1.675 + 0.0373 × age (years) + 0.0943 BMI (kg/m2) + 1.133 × impaired fasting glycaemia or diabetes (yes = 1, no = 0) + 0.993 × AST/ALT ratio − 0.0133 × platelet (×109/L) − 0.663 × albumin (g/dL)." (PMID 32933184, 2020). "NFS was calculated by the formula: 1.675 + 0.037 × age (years) + 0.094 × BMI (kg/m2) + 1.13 × impaired fasting glucose/diabetes (yes = 1, no = 0) + 0.99 × AST/ALT ratio − 0.013 × platelet count (×109/L) − 0.66 × albumin (g/dL)." (PMID 32570776, 2020). "The ALB/GLB ratio was lower than normal in three patients (7.50%) without diabetes and seven patients (17.50%) with diabetes." (PMID 33376750, 2020). "In our study, the presence of diabetes, American Society of Anesthesiologists (ASA) score, neo-adjuvant therapy, or albumin level were not identified as factors in biliary candidiasis." (PMID 33007843, 2020). "The other baseline characteristics, such as BMI (p = 0.593), presence of diabetes (p = 0.292), hypertension (p = 0.711), HGB (p = 0.118), and preoperative albumin (Alb) level (p = 0.759) were also not significantly different." (PMID 32093662, 2020). "Patients with DPN were significantly older and had longer duration of diabetes, higher FPG and urine albumin levels, compared to those without it (all p <0.05 at least)." (PMID 30571795, 2018). "Several dialysis comorbidities, such as diabetes, COPD, and low albumin, were not considered as comparative mortality predictors." (PMID 30115036, 2018). "In the present study, CKD patients with diabetes had lower serum albumin and a higher proportion of hypomagnesemia and osteoporosis than those of CKD patients without diabetes." (PMID 26273297, 2015). "Coronary artery calcification was predicted by age, gender, and diabetes, but not by parameters related to renal function, including eGFR, calcium, phosphorous, i-PTH, hemoglobin, and albumin." (PMID 26042415, 2015). "We also did not account for other measurements (such as diabetes status, HDL cholesterol, triglycerides and urinary albumin-creatinine ratio), though none of these measurements were significantly associated with adult cardiac structure in the Bogalusa study." (PMID 25191997, 2014). "Compared with individuals without diabetes, urine AGT concentration is also increased in people with type 1 diabetes and normal urine albumin excretion." (PMID 24793984, 2014). "Based on our results, 8 months of HFFD diet in C57BL/6 mice corresponds best to human stage 1 renal changes in diabetes (hyperfiltration, absence of thickened GBM and slightly elevated urinary albumin)." (PMID 24098551, 2013). "-1.675 + 0.037 × age (years) + 0.094 ×BMI (kg/m2) + 1.13 × IFG/diabetes (yes = 1, no = 0) + 0.99 × AST/ALT - 0.013 × platelet count (× 109/L) - 0.66 × albumin (g/dL)." (PMID 22221544, 2012). "High quality studies that obtain serial determinations of urinary albumin/creatinine ratios in HIV-infected patients both with and without diabetes are needed to better estimate the prevalence of this problem." (PMID 21931772, 2011). "Seven mechanically ventilated critically ill patients, not previously known to have diabetes, received two intravenous infusions of GLP-1 (1.2 pmol/kg/min) and placebo (4% albumin) over 270 minutes." (PMID 19439067, 2009).
diabetes (continued). "The low-SPPB group with or without diabetes was more likely to be older, with a higher level of MIS and CCI; a higher percentage of low muscle mass; and a lower level of serum creatinine, BUN, uric acid, and serum albumin than the high-SPPB group." (PMID 39625793, 2025). "Additionally, stress hyperglycemia, as measured by glucose/glycated albumin ratio, exhibited a significant U-shaped relationship only in ACS patients with diabetes mellitus, as opposed to those without diabetes, which partially aligns with our findings." (PMID 40303637, 2025). "Compared with Group 1, Group 3 participants were more likely to be older men with higher income levels, no alcohol drinking, no diabetes, hypertension, taking prescribed medication, lower prevalence of anemia and more urinary system cancers, and lower LMR, ALB and TC, but higher NLR (P < 0.05)." (PMID 40018412, 2025). "Instead the following features were import to predict CVD in people with diabetes but without a history of CVD (“w T2DM”): HbA1c, cystatin C, self-reported health satisfaction, biochemical measures of ill health e.g. plasma albumin (representing liver and kidney damage)." (PMID 40082712, 2025). "Furthermore, ALB levels were low in T2D-DED patients, as previously demonstrated in numerous diabetes studies, compared to non-diabetic patients, because insulin deficiency is involved in reducing ALB synthesis in the liver." (PMID 40792303, 2025). "However, the ability of BAR to predict the progression of diabetes in our study was inferior to the existing gold standard, HbA1c, and did not demonstrate the significant predictive power independent of BUN and albumin." (PMID 39796544, 2024). "Compared with NNIG patients, there was a significant improvement in blood phosphorus, ALB, UAV, and RFF in the NIG group, regardless of whether the patients had diabetes or not." (PMID 39512519, 2024). "Furthermore, stress hyperglycemia, as measured by glucose/glycated albumin ratio, exhibited a significant U-shaped relationship only in ACS patients with diabetes mellitus, as opposed to those without diabetes, which partially aligns with our findings." (PMID 37891639, 2023). "TP (64.17 vs 59.36g/L, P < 0.001) and albumin (37.81 vs 35.42 g/L, P = 0.014) were higher, while VFA was lower (78.07 vs 95.98 cm2, P = 0.004) in patients with leukemia combined without diabetes than in patients with diabetes." (PMID 35308284, 2022). "The presence of MVC was a significant factor associated with all-cause mortality (HR: 1.517, P = 0.010), in addition to old age, diabetes history, CVD history, no use of vitamin D medications, increased LAD, decreased HGB, increased β2-microglobulin and decreased ALB." (PMID 35065601, 2022). "The presence of AVC was a significant factor associated with all-cause mortality (HR: 1.433, P = 0.028) in addition to old age, diabetes history, CVD history, no use of vitamin D medications, increased LAD, decreased HGB, increased β2-microglobulin and decreased ALB." (PMID 35065601, 2022). "CBPB was particularly associated with a decreased risk of osteoporosis in patients with longer hemodialysis vintage, lower serum albumin level, lower intact PTH level, and active vitamin D analog use as well as in non-CVD, non-diabetes mellitus, and non-PPI use patients." (PMID 33462371, 2021). "However, diabetes, obesity, CHD, hypertension and NAFLD did not correlate with liver-related events as well as sex, HBeAg status, ALT, GGT, albumin or MELD score." (PMID 33946154, 2021). "Age-affected 18 variables include comorbidity, hypertension, diabetes, lymphocyte, CD4+ and CD8+ T cells, IL8, TNFα, eGFR, hemoglobin, albumin, CK-MB, onset to admission, onset to PCR negative, discharged, secondary infection, acute kidney injury, and acute liver injury." (PMID 34025688, 2021). "Differences in ALB, BUN, CREA, and diabetes history were not significant between the two groups." (PMID 34658782, 2021).
diabetes (continued). "Other variables such as age, gender, albumin level, BMI, lactate dehydrogenase (LDH) level, gastrointestinal malignancy, performance status, hormonal therapy, radiotherapy, surgery, diabetes, hypertension, and cardiac disorders were not statistically significant." (PMID 34444556, 2021). "No consistent relationships between PBUT plasma concentrations and dialysis vintage, medications, plasma albumin, blood pressure, history of CVD, diabetes mellitus, and inflammation were observed, as well as not after adjustment for protein intake (nPNA) or stratification for RKF." (PMID 32272776, 2020). "We found that the test indexes PCV, albumin globulin ratio, HDL-cholesterol, triiodothyronine, and fibrinogen differ significantly between people with and without diabetes; hence, these indexes can be used as important reference risk factors for diabetes mellitus." (PMID 29587624, 2018). "TGs were also inversely associated with infectious mortality in the univariate model (HR: 0.75; 95% CI: 0.69–0.81), as well as in the models adjusted for demographics, diabetes, serum creatinine, and CRP (models 1–3 and 5) but not following adjustment for serum albumin (models 4 and 6)." (PMID 29895699, 2018). "In addition, participants with diabetes had a lower GFR and a greater urine albumin excretion (p<0.01 for both) compared with the non-diabetic controls." (PMID 25607823, 2015). "GSE142025 enabled the RNA sequencing analysis of kidney tissues from DN patients with micro- [urinary albumin-to-creatinine ratio (UACR) of 30–300 mg/g] and macro-albuminuria (UACR >300 mg/g) compared with unaffected tissues obtained from the tumor nephrectomies of patients without diabetes." (PMID 35711407, 2022). "Compared with nondiabetics, patients with diabetes were older and had high levels of fasting plasma glucose (FPG), D-dimer, white blood cells, blood urea nitrogen (BUN), and total bilirubin (TBIL) and lower levels of lymphocytes, albumin and oxygen saturation (SaO2), and higher mortality (P < 0.05)." (PMID 32851093, 2020). "Besides, a range of indicators was significantly different among diabetes and non-diabetic groups, such as the age distribution, race, comorbidity, peripheral blood indicators (WBC, NEUT%, LY%, Hb, PLT, K, BE, AG, BUN, Scr, ALB, and Tbil), and heart rate (p < 0.05)." (PMID 34778320, 2021). "Additionally, patients with relatively older age, no diabetes, peritoneal UF of less than 1000 mL/day, and low serum creatinine, total cholesterol, serum ferritin, and hs-CRP levels, survival rate was found to increase along with increasing serum albumin level." (PMID 29694445, 2018).